IFI27 (interferon alpha inducible protein 27)
Diseases named in the same sentence as IFI27 in open-access papers (continued):
Sharing a sentence is not in itself a finding about the gene and the disease.
oral cancer (3 papers, 2018 to 2023). "In oral cancer, high expressions of ISG15, IFI27, and OASL were associated with low expressions of ATM, the activation of inflamed immune pathways, and increased tumor-infiltrating scores of CD8+ T, natural killer, and dendritic cells." (PMID 37174688, 2023). "The effect of ISG15/IFI27/OASL expression on the configurations of tumor-infiltrated lymphocytes in oral cancer was examined using the cell-type enrichment analysis algorithm xCell." (PMID 37174688, 2023). "In oral cancer, high expressions of ISG15, IFI27, and OASL were found to be associated with low ATM expression (mimicry of ATM inhibition), the activation of inflamed immune pathways, and elevated tumor-infiltrated scores of pDC, NK, and CD8+ T cells." (PMID 37174688, 2023). "Among these ISGs, the high expressions of ISG15, IFI27, and OASL were associated with low ATM expression, the activation of immune pathways, and high tumor-infiltrating scores of DCs, NK, and cytotoxic CD8+ T cells in oral cancer." (PMID 37174688, 2023). "The effect of IFI27 downregulation on oral cancer cell invasion was detected using Transwell assay." (PMID 29580248, 2018). "The induction of ISG15, IFI27, and OASL expression by KU55933 was also observed in oral cancer cells CAL27 and derived CDDP-R cancer cells." (PMID 37174688, 2023).
pancreatic ductal adenocarcinoma (3 papers, 2021 to 2025). An infiltrating adenocarcinoma that arises from the epithelial cells of the pancreas. "IFI27 showed high expression in ductal cells and fibroblasts, whereas KLK10 was strongly expressed in ductal cells, suggesting that IFI27 and KLK10 could be closely linked to the development of pancreatic ductal carcinoma." (PMID 41008826, 2025).
tongue squamous cell carcinoma (3 papers, 2018 to 2024). A squamous cell carcinoma that arises from the tongue. "The most differentially upregulated genes were IFI6 and IFI27, which play an important role in apoptosis and may promote the growth and migration of tongue squamous cell carcinoma." (PMID 38254880, 2024). "Here we discovered that ATF3 plays an anti-tumor role in tongue squamous cell carcinoma (TSCC) cells through the transcriptional suppression of its new downstream targets interferon alpha inducible proteins 6 (IFI6) and 27 (IFI27)." (PMID 33539340, 2021).
ZIKV infection (3 papers, 2018 to 2025). "The results showed that all genes were significantly upregulated in the infected group, with IFI44 and IFI27 showing the most significant upregulation, indicating that these genes may be involved in the regulation of the host’s response to ZIKV infection in the nervous and immune systems." (PMID 41573570, 2025). "During ZIKV infection in this individual, there was similar strong induction of type I ISGs, exemplified by MX1, OAS3, RSAD2, and IFI27 genes (Cluster 2), but minimal coincident induction of chemokines involved in leukocyte chemotaxis (Cluster 1)." (PMID 30596671, 2018).
Aicardi-Goutières syndrome (2 papers, 2021 to 2023). "We next examined baseline gene expression (qPCR) of archetypal interferon stimulated genes (ISGs) IFI27, USP18, MX1, OASL, IRF7, and MX2, and those ISGs found highly expressed in PBMCs from the type 1 interferonopathy, Aicardi-Goutières syndrome (AGS) patients (IFI27, ISG15, IFI44L, and RSAD2)." (PMID 33746960, 2021).
bladder cancer (2 papers, 2017 to 2024). "Nevertheless, the specific influence of IFI27 on Treg cells in bladder cancer (BCa) remains elusive." (PMID 39668835, 2024). "Flow cytometric analysis further demonstrated that IFI27 inhibits bladder cancer progression by suppressing regulatory T cell infiltration and enhancing anti-tumor immune responses." (PMID 39668835, 2024). "Subsequently, we investigated the inhibitory effects of IFI27 on bladder cancer proliferation, migration, epithelial-mesenchymal transition, and lymph node metastasis." (PMID 39668835, 2024). "In conclusion, these findings establish IFI27 as a promising molecular marker for improving the efficacy of immunotherapy in bladder cancer and offer valuable insights into strategies for enhancing immunotherapy sensitivity." (PMID 39668835, 2024). "Further analysis demonstrated that IFI27 is predominantly expressed in the cytoplasm of bladder cancer cells and exhibited low expression levels in bladder cancer tissues and cell lines." (PMID 39668835, 2024). "These points suggest that IFI27 may be involved in regulating FOXP3 expression in bladder cancer, which requires further studies in the future." (PMID 39668835, 2024). "In bladder cancer cells, DAC treatment increased the double-stranded RNA sensors, MDA5, MAVS and RIG-1, intermediate mediator IRF7, and downstream targets IFI44 and IFI27 and IFN-γ by 2-fold to 70-fold compared to control cells." (PMID 29242529, 2017).
Cirrhosis (2 papers, 2023 to 2025). A chronic disorder of the liver in which liver tissue becomes scarred and is partially replaced by regenerative nodules and fibrotic tissue resulting in loss of liver function. "Additionally, immune infiltration highlighted a strong correlation between macrophages and cirrhosis, with the identifying genes (COX7A1 and IFI27) being significantly associated with macrophages." (PMID 38275754, 2023). "Subsequently, RT-PCR analysis of the liver tissue revealed increased IFI27 and COX7A1 expression in the TAA-treated cirrhosis group compared to the control group." (PMID 38275754, 2023).
co-infection (2 papers, 2018 to 2025). "IFI27 is involved in the IFN pathway and was found to be up-regulated in HCC, indicating that IFI27/IFN could be a valuable indicator of co-infection-associated immune changes." (PMID 30138348, 2018). "Our qRT-PCR analysis with the patient samples showed that expression of IFI27 was elevated 6.2 fold at the advanced stage of co-infection, compared with the same stage of mono-infection, which was again consistent with the microarray data, wherein the increase was approximately 3 fold." (PMID 30138348, 2018).
colon cancer (2 papers, 2021 to 2024). "DDX58, XAF1, OAS1, IFI27, IFI44 or IFIT3 was indeed downregulated and CHST4 or TNFSF18 was upregulated in MDM4 overexpressed colon cancer cells." (PMID 38281029, 2024). "We selected eight representative immune-related molecules for qPCR validation in SW480 and another colon cancer cell line HT29: DDX58, CHST4, TNFSF18, XAF1, OAS1, IFI27, IFI44, IFIT3." (PMID 38281029, 2024).
dermatomyositis (2 papers, 2022 to 2024). Dermatomyositis (DM) is a type of idiopathic inflammatory myopathy characterized by evocative skin lesions and symmetrical proximal muscle weakness. "RNA-Seq transcriptome comparison of polymyositis and dermatomyositis has shown dermatomyositis-specific increases in OASL, EPSTI1, and IFI27 within CD8 + T cells." (PMID 34997119, 2022).
hepatitis C (2 papers, 2021). "In a previous report, IFI27 was first proposed to have antiviral activity against Sindbis virus infection in mice that can also reduce infection of hepatitis C, though the basic mechanisms remain unidentified." (PMID 33868214, 2021).
latent infection (2 papers, 2014 to 2024). "Our findings revealed that BNRF1 promoted robust proliferation of the B-cells that were transformed by EBV latent infection via IFI27 upregulation both in vitro and in vivo." (PMID 38300891, 2024). "Moreover, we profiled the IRF4 transcriptome in the context of EBV latent infection, and confirmed several genes including IFI27, IFI44, GBP1, and ARHGAP18, as well as CFLAR as novel targets for IRF4." (PMID 25207815, 2014).
Liver Cirrhosis (2 papers, 2017 to 2023). "In conclusion, our findings underscore the critical role of oxidative stress-related mitochondrial genes (COX7A1 and IFI27) in liver cirrhosis development, highlighting their association with macrophage infiltration." (PMID 38275754, 2023). "Finally, two oxidative stress-related mitochondrial genes COX7A1 and IFI27 were selected as identifying genes associated with liver cirrhosis." (PMID 38275754, 2023). "Collectively, these data suggest that aberrant COX7A1 and IFI27 expression impacts immune activity related to liver cirrhosis, identifying them as promising identifying genes for understanding this association." (PMID 38275754, 2023). "Compared with the control samples, the expression levels of COX7A1 and IFI27 were significantly upregulated in the liver cirrhosis samples in both the merged dataset and validation dataset GSE89377." (PMID 38275754, 2023). "Therefore, these mitochondrial oxidative stress-related genes, COX7A1 and IFI27, have pivotal roles in the development of liver cirrhosis." (PMID 38275754, 2023). "Finally, COX7A1 and IFI27 emerged as identifying genes for liver cirrhosis, validated through a receiver operating characteristic (ROC) curve analysis and related experiments." (PMID 38275754, 2023). "We found that COX7A1 and IFI27 may be potential candidate identifying genes, and immune cell infiltration analysis elucidated the strong correlation of macrophages in the development of liver cirrhosis." (PMID 38275754, 2023). "Thus, we speculate that IFI27 likely plays a central role in modulating hepatic macrophage polarization, influencing liver cirrhosis progression." (PMID 38275754, 2023). "In this study, IFI27 and COX7A1 were observed to exhibit higher expression levels within liver cirrhosis samples compared to the normal group." (PMID 38275754, 2023). "To further elucidate the potential implications of IFI27 and COX7A1 in liver cirrhosis, we established a TAA-induced mouse liver cirrhosis model." (PMID 38275754, 2023). "Our investigation revealed increased levels of both IFI27 and COX7A1 in liver cirrhosis." (PMID 38275754, 2023).
polymyositis (2 papers, 2022 to 2023). A rare idiopathic inflammatory myopathy characterized by symmetric proximal muscle weakness and elevated muscle enzymes. "Using microarrays, IFIG expression levels (including ISG5, Mx1, OAS1, IFIT4, IFIT1, IFI44, OAS3, OAS2, IRF7, and IFI27) in muscle samples were higher in DM than in other inflammatory myopathies, such as inclusion body myositis, polymyositis, necrotizing myopathy, and myopathies with inflammation." (PMID 36979843, 2023). "Another study reported that the breakdown of positive IFN-I signatures (top five IFIGs were IFI6, RSAD2, STAT2, IFI44, and IFI27) in whole blood of patients were 73% SLE, 68% SSc, 66% DM, 61% polymyositis (PM), and 33% RA." (PMID 36979843, 2023).
squamous cell carcinoma (2 papers, 2014 to 2024). A carcinoma arising from squamous epithelial cells. "ATF3 regulates the biological behavior of human squamous cell carcinoma through the downregulation of IFI27." (PMID 38226966, 2024).
Stroke (2 papers, 2023 to 2025). Sudden impairment of blood flow to a part of the brain due to occlusion or rupture of an artery to the brain. "Machine learning technique, LASSO regression analysis, was utilized to refine our search, leading to the identification of three genes, EIF2AK2, PARP9, and IFI27, which demonstrated strong diagnostic potential confirmed by ROC curves in both stroke and SLE cohorts." (PMID 40313968, 2025). "The correlation analysis indicated an inverse relationship between the genes EIF2AK2, PARP9, and IFI27 and the presence of M2 macrophages within the stroke dataset." (PMID 40313968, 2025). "In conclusion, our study suggests that aging stroke may be regulated by IFI27 and OAS2 via the type I interferon signaling pathway." (PMID 36862915, 2023). "In the stroke validation set (GSE58294), the AUC values for EIF2AK2, PARP9, and IFI27 were 0.761, 0.689, and 0.584, respectively." (PMID 40313968, 2025). "In the stroke-GSE16561 dataset, the AUC values for EIF2AK2, PARP9, and IFI27 were 0.862, 0.797, and 0.685, respectively, all exceeding 0.6." (PMID 40313968, 2025). "Together, these hub genes (EIF2AK2, PARP9, and IFI27) are integral to the regulation of autoimmune and inflammatory responses, representing potential biomarkers for SLE with concomitant stroke." (PMID 40313968, 2025). "This study marks the first exploration of hub genes in the context of stroke and SLE, suggesting EIF2AK2, PARP9, and IFI27 as potential biomarkers for further investigation into the mechanistic underpinnings of their comorbidity." (PMID 40313968, 2025). "IFI27, an interferon-inducible gene, plays a pivotal role in regulating cellular responses to interferons, and its closely related family member IFI27L2A is upregulated in microglia after a stroke." (PMID 40313968, 2025).
vitiligo (2 papers, 2022 to 2023). Generalized well circumscribed patches of leukoderma that are generally distributed over symmetric body locations and is due to autoimmune destruction of melanocytes. "Inflammatory and immune response–related genes such as CD74, IFI27, IFI6, and IFITM1 were also significantly increased, and this was further confirmed by the hallmark pathway enrichment analysis of the genes highly expressed in vitiligo lesional skin using the Molecular Signatures Database (MSigDB)." (PMID 35653192, 2022). "We noted that other genes, such as Lnc-ARRDC3-1, PLCG1, A_33_P3229958, TERM1, and RAB13, showed increased expression, whereas TM4SF19, IFI27, and IL17RB showed decreased expression in T cells from patients with vitiligo compared with the controls." (PMID 37731844, 2023).
allergic asthma (1 paper, 2022). A asthma with a basis in a pathological type I hypersensitivity reaction. "MX1, RSAD2, IFIT1, IFI27, OAS3, and SAMD9L were markedly elevated in HDM-treated mice and positively associated with IL-5, IL-13 and MUC5AC (key mediators of allergic asthma)." (PMID 36211429, 2022). "Furthermore, MX1, RSAD2, IFIT1, IFI27, OAS3, and SAMD9L levels correlated positively with IL-5, IL-13, and MUC5AC levels, which are the key mediators of allergic asthma." (PMID 36211429, 2022).
aneurysm (1 paper, 2023). Bulging or ballooning in an area of an artery secondary to arterial wall weakening. "IFI27 has also been reported as differentially expressed between chronic ruptured aneurysm and control blood samples, further suggesting its importance in IA progression to rupture." (PMID 36836499, 2023).
bacterial sepsis (1 paper, 2023). "Overall, among ICU patients, S100A12 activation could be even stronger in certain patients within the negative groups (such as bacterial sepsis), while IFI27 activation was more restricted to the positive group." (PMID 36649304, 2023).
bladder tumors (1 paper, 2024). "In short, upregulation of IFI27 expression suppressed bladder tumor proliferation and lymph node metastasis in vivo." (PMID 39668835, 2024). "In conclusion, IFI27 exhibits anticancer effects in bladder tumors by inhibiting tumor growth and preventing the epithelial-mesenchymal transition (EMT)." (PMID 39668835, 2024). "Given the increasingly prominent regulatory role of IFI27 in Treg cell enrichment within the tumor immune microenvironment, we aimed to explore whether IFI27 exerts a suppressive effect on Treg cell frequency in bladder tumors." (PMID 39668835, 2024).
celiac disease (1 paper, 2023). An autoimmune genetic disorder with an unknown pattern of inheritance that primarily affects the digestive tract. "Similar to celiac disease, expression levels of GBP5, CXCL10, IFI27, and IFNG were increased in tissues of patients with no or low-grade intestinal injury." (PMID 36282455, 2023).
cervical cancer (1 paper, 2023). A primary or metastatic malignant neoplasm involving the cervix. "The high expressions of ISG15, IFI27, and OASL were also correlated with complete remission in patients with cervical cancer treated with cisplatin." (PMID 37174688, 2023). "Since KU55933 induced the expressions of ISG15, IFI27, and OASL in CDDP-R cancer cells, the effects of the three ISGs on the response to cisplatin therapy were examined in patients with cervical cancer from the TCGA cohort." (PMID 37174688, 2023). "This study also found that high expressions of ISG15, IFI27, and OASL were associated with complete remission in patients with cervical cancer treated with cisplatin but not in those without cisplatin-based therapy." (PMID 37174688, 2023).
chronic kidney disease (1 paper, 2016). Impairment of the renal function secondary to chronic kidney damage persisting for three or more months. "Second, although we evaluated the IFI27 levels in many other chronic kidney diseases, including MK and TN, the distributions of IFI27 levels in these diseases were not well defined because of the small number of patients analyzed." (PMID 27100186, 2016).
diabetic kidney disease (1 paper, 2024). Progressive kidney disorder caused by vascular damage to the glomerular capillaries, in patients with diabetes mellitus. "And a negative correlation between IFI27 expression and GFR(MDRD) was found in the tubule of con and diabetic kidney disease from the Nephroseq database." (PMID 38270638, 2024).
dysplasia (1 paper, 2025). A usually neoplastic transformation of the cell, associated with altered architectural tissue patterns. "For instance, biomarkers such as IFI27 and ATF3 differentiated metaplasia from dysplasia with statistically significant p-values (p = 0.009 and p = 0.003, respectively), revealing their potential utility in dysplasia diagnosis." (PMID 40620772, 2025).
Ebola (1 paper, 2024). "Given the crucial role of interferon-stimulated genes like IFI27 in the innate immune response, its significant expression in Ebola-infected NHPs could reflect an activation of defense mechanisms against the virus." (PMID 39282474, 2024).
endothelial dysfunction (1 paper, 2025). In vascular diseases, endothelial dysfunction is a systemic pathological state of the endothelium (the inner lining of blood vessels) and can be broadly defined as an imbalance between vasodilating and vasoconstricting substances produced by (or acting on) the endothelium. "These DORs were located at promoters of genes including CD74, IFI27, HLA-DMA, CASP8 and NOX4, which are associated with antigen presentation, inflammation and endothelial dysfunction." (PMID 41085167, 2025).
enterovirus infection (1 paper, 2021). "Type I-IFN plays a critical role in the innate immune response as the first line of defense against enterovirus infection and regulates many immune responsive genes, including IFN-β, IFI-27, ISG15, and OAS-1." (PMID 34485180, 2021).
fungal infections (1 paper, 2024). "More studies with different respiratory and non-respiratory viral, bacterial, and fungal infections will be required to confirm IFI27 as robust diagnostic biomarker." (PMID 39192977, 2024).
glioblastoma (1 paper, 2022). The most malignant astrocytic tumor (WHO grade IV). "Atypical EGFR signaling in glioblastoma activates the transcription factor IRF3, leading to the expression of IFI27, which often plays an important oncogenic role." (PMID 36291283, 2022).
glioma (1 paper, 2005). A benign or malignant brain and spinal cord tumor that arises from glial cells (astrocytes, oligodendrocytes, ependymal cells). "In this study on glioma cells, the activation of numerous interferon-induced proteins (such as IFIT1, IFIT2, IFI27, IFITM1, IFITM2, and G1P2) lends support to this mechanism of pathogenicity." (PMID 15829208, 2005).
glomerulonephritis (1 paper, 2016). A renal disorder characterized by damage in the glomeruli. "Our results suggest that a lower level of IFI27 in PBMCs might be a good marker for CGN, especially IgAN, the most common primary glomerulonephritis." (PMID 27100186, 2016).
interstitial nephritis (1 paper, 2024). Inflammation of the renal tubules and supporting tissues of the kidney. "In consequence, IFI27 could be a potential biomarker to differentiate ICPI-interstitial nephritis from rejection." (PMID 39654653, 2024).